ZNF300P1 (zinc finger protein 300 pseudogene 1)
Gene: Transcribed unprocessed pseudogene on chromosome 5 (150,930,763 to 150,946,289, reverse strand). Ensembl gene ENSG00000197083.
Diseases named in the same sentence as ZNF300P1 in open-access papers:
ZNF300P1 is named in the same sentence as 5 diseases in open-access papers, as found by Europe PMC text mining. Sharing a sentence is not in itself a finding about the gene and the disease. The quoted sentences say what the papers report.
ovarian carcinoma (5 papers, 2014 to 2018). A malignant neoplasm originating from the surface ovarian epithelium. "The transcriptional analyses undertaken within this study, using siRNA against ZNF300P1, indicate that loss of ZNF300P1 expression, as seen resulting from hypermethylation in ovarian cancer samples, results in both up- and down- regulated gene expression." (PMID 24393131, 2014). "Here, we investigate the novel role that ZNF300P1 repression may play in ovarian cancer development and progression, and show that lincRNA ZNF300P1 plays a role in regulating cell polarity, and how loss of expression may contribute to the metastatic potential of ovarian cancer cells." (PMID 24393131, 2014). "It is also involved in the attachment of ovarian cancer cells to peritoneal membranes, suggesting a probable function of ZNF300P1 expression in metastasis of ovarian cancer cells to sites within the peritoneal cavity." (PMID 27664137, 2017). "Our studies reveal that ZNF300P1 is enriched in the nucleus, lending further support to a potential functional role in ovarian cancer." (PMID 24393131, 2014). "We applied methylated DNA immunoprecipitation on whole genome promoter tiling arrays and Sequenom assays to examine methylation status of ZNF300P1 in multiple ovarian cancer cell lines, as well as in normal ovarian and ovarian tumor tissues." (PMID 24393131, 2014). "We have demonstrated that the lincRNA ZNF300P1 is frequently hypermethylated and silenced in ovarian cancer." (PMID 24393131, 2014). "We have determined that suppression of ZNF300P1 in ovarian cancer cells results in decreased proliferation and colony formation, as well as loss of cellular polarity." (PMID 24393131, 2014). "We also reveal a novel role for ZNF300P1 in the adhesion of ovarian cancer cells to the peritoneal membrane, suggesting a potential function in ovarian cancer metastasis." (PMID 24393131, 2014). "Transcript profiling was used to investigate the effects of ZNF300P1 suppression in ovarian cancer cells." (PMID 24393131, 2014). "We previously identified that the CpG island-associated promoter of the novel lincRNA ZNF300P1 (also known as LOC134466) is frequently hypermethylated and silenced in ovarian cancer tissues." (PMID 24393131, 2014). "We demonstrate that ZNF300P1 is methylated in multiple ovarian cancer cell lines." (PMID 24393131, 2014). "Using an ex vivo peritoneal adhesion assay, we also reveal a role for ZNF300P1 in the attachment of ovarian cancer cells to peritoneal membranes, indicating a potential function of ZNF300P1 expression in metastasis of ovarian cancer cells to sites within the peritoneal cavity." (PMID 24393131, 2014). "Together, these results provide the first evidence of the downstream biological effects of methylation-mediated repression of ZNF300P1 in ovarian cancer, and implicate the specific targeting of the transcript, and the resultant loss of expression, as a critical step in EOC progression." (PMID 24393131, 2014). "As a candidate lincRNA, we hypothesized that a reduction of ZNF300P1 expression, as seen in ovarian cancer cell lines, would recapitulate transcriptional network and the cell phenotype aberrations observed in cells harboring ZNF300P1 DNA methylation." (PMID 24393131, 2014). "The transcript profiles from the same study showed that this hypermethylation was indeed associated with repression of gene expression, suggesting that regional epigenetic silencing may occur near ZNF300P1 in ovarian cancer." (PMID 24393131, 2014). "Given that ZNF300 is up-regulated in cancer, and promotes inflammation and metastasis, the repression of ZNF300P1 associated with methylation in ovarian cancer make it unlikely to be functioning as an miRNA decoy." (PMID 24393131, 2014). "ZNF300P1 has also been demonstrated to be involved in the regulation of important cell cycle and cell motility networks in human ovarian surface epithelial cells and may participate in promoting metastasis in ovarian cancer cells." (PMID 27664137, 2017).
ovarian carcinoma (continued). "The novel lincRNA ZNF300P1 is frequently hypermethylated in multiple ovarian cancer tissues and cell lines, and its expression can influence cell polarity, motility, and adhesion, while loss of expression may contribute to the metastatic potential of ovarian cancer cells." (PMID 27686732, 2016). "In addition, a pseudo-gene of the human ZNF300, ZNF300P1, which shares 89% identity with ZNF300, is a long-intergenic non-coding RNA that is frequently methylated in ovarian cancer, indicating a potential role for ZNF300P1 expression in regulating ovarian cancer cell metastasis." (PMID 27982099, 2016). "Our findings further support ZNF300P1 as frequently methylated in ovarian cancer and reveal a novel function for ZNF300P1 lincRNA expression in regulating cell polarity, motility, and adhesion and loss of expression may contribute to the metastatic potential of ovarian cancer cells." (PMID 24393131, 2014). "In this report we demonstrate that ZNF300P1 is involved in the regulation of key cell cycle and cell motility networks in human ovarian surface epithelial cells, and may play a role in promoting metastasis in ovarian cancer cells." (PMID 24393131, 2014).
ovarian tumors (1 paper, 2014). "We therefore performed a detailed analysis of methylation of ZNF300P1 in primary ovarian tumors to determine its tendency in clinical EOC samples." (PMID 24393131, 2014).
small cell lung carcinoma (1 paper, 2014). Small cell lung cancer (SCLC) is a highly aggressive malignant neoplasm, accounting for 10-15% of lung cancer cases, characterized byrapid growth, and early metastasis. "Interestingly, ZNF300P1 was recently identified as methylated in small cell lung cancer-derived cell lines potentially indicating that loss of expression of this transcript may be common to several cancer types." (PMID 24393131, 2014).
cancer (2 papers, 2014 to 2016). A tumor composed of atypical neoplastic, often pleomorphic cells that invade other tissues. "The major phenotypic outcomes we identified to be associated with ZNF300P1 silencing was decreased polarity and the resultant loss of migratory persistence, both key in cancer development and the aberrant spread of cancer cells." (PMID 24393131, 2014). "Evidence of hypermethylation at the CpG island associated with ZNF300P1 was observed in both cancer cell lines, however hypermethylation of neighboring CpG islands (ZNF300 and GPX3) was only observed in A2780 cells." (PMID 24393131, 2014). "We sought to determine the role that ZNF300P1 might play on cancer cell processes including proliferation and motility." (PMID 24393131, 2014). "To investigate whether ZNF300P1 methylation was embedded in a region of LRES in EOC, we evaluated methylated DNA immunoprecipitation on whole genome promoter tiling array (MeDIP-ChIP) profiles for normal ovarian surface epithelium (OSE) and A2780 and CaOV3 cancer cell lines as described." (PMID 24393131, 2014).
tumor (2 papers, 2014 to 2018). "While repression of the lincRNA clearly affected the ability of cells to proliferate and form colonies, it had no discernible effect on the cell cycle, indicating that ZNF300P1 does not function as a classic tumor suppressor." (PMID 24393131, 2014).